OXT (oxytocin/neurophysin I prepropeptide)
Description:
Precursor of oxytocin, a neurohypophyseal hormone that plays a key role in social interactions and neurophysin 1, its carrier protein. [Oxytocin]: Neuropeptide hormone released by the posterior pituitary gland that plays a key role in social behavior and other biological processes, such as milk ejection. Released in response to a variety of social cues and acts by binding to oxytocin receptor (OXTR), triggering signaling that modulates neural circuits by altering ion channel activity, changing intrinsic neuronal properties and modifying synaptic transmission (both excitatory and inhibitory). Central release (direct secretion in the brain) plays essential roles in social behavior, such as maternal care, social cognition and affiliative behaviors. Stressful and anxiogenic stimuli promote release of oxytocin, which acts as a powerful modulator of anxiety- and stress-related behaviors. Oxytocin promotes altruism by enhancing empathy, trust and social bonding, making people more generous. Can also favor parochial altruism, a social behavior involving costly helping of one's own group (in-group) that often comes with hostility or discrimination towards other groups (out-groups). Modulates neural circuits related to reward, fear and social approach, encouraging care and cooperation, but can also increase guilt or aggression towards out-groups. Beyond its role in social behavior, plays a role in other processes, such as parturition, lactation or osteoblast differentiation, when released peripherally (secreted from the posterior pituitary gland into the bloodstream). Required for parturition and milk ejection by triggering and strengthening contraction of the smooth muscle of the uterus and mammary gland, respectively. Promotes bone mass by stimulating bone formation by osteoblasts (By similarity). [Neurophysin 1]: Carrier protein that binds to and transports oxytocin from the hypothalamus to the posterior pituitary gland, protecting it from degradation and facilitating its release.
Synonyms: OT-NPI; OT; OXT-NPI
Tractability: Antibody: its Gene Ontology location is reachable by antibodies, with high confidence; UniProt places it where antibodies can reach, with medium confidence; UniProt predicts a signal peptide or a membrane-spanning region.
Gene: Protein-coding gene on chromosome 20 (3,071,620 to 3,072,517, forward strand). Ensembl gene ENSG00000101405.
Subcellular location: Cytoplasmic vesicle, secretory vesicle; Secreted (Oxytocin); Secreted (Neurophysin 1)
Pathways (Reactome):
Signal Transduction: G alpha (q) signalling events; Vasopressin-like receptors
Gene Ontology:
Molecular function: protein binding; neuropeptide hormone activity; oxytocin receptor binding; neurohypophyseal hormone activity
Biological process: intracellular signal transduction; maternal aggressive behavior; positive regulation of cold-induced thermogenesis; positive regulation of uterine smooth muscle contraction; signal transduction; drinking behavior; eating behavior; female pregnancy; grooming behavior; heart development; male mating behavior; maternal behavior; memory; negative regulation of blood pressure; negative regulation of urine volume; positive regulation of blood pressure; positive regulation of cytosolic calcium ion concentration; positive regulation of female receptivity; positive regulation of hindgut contraction; positive regulation of norepinephrine secretion; positive regulation of ossification; positive regulation of penile erection; positive regulation of prostaglandin secretion; positive regulation of synapse assembly; positive regulation of synaptic transmission; and 19 more
Cellular component: extracellular region; secretory granule; cytoplasm; neuronal dense core vesicle; terminal bouton; transport vesicle
Genetic constraint (gnomAD): Loss-of-function variants: 13 observed, 9.05 expected, observed/expected ratio (o/e) 1.44, 90% interval 0.91 to 1.91. That is too few expected variants to judge how well the gene tolerates losing a copy. Missense variants: 175 observed, 125.01 expected, observed/expected ratio (o/e) 1.4, 90% interval 1.24 to 1.59. Synonymous variants: 76 observed, 56.68 expected, observed/expected ratio (o/e) 1.34, 90% interval 1.11 to 1.62.
Homologues: Orthologues: chimpanzee OXT (98% identical), macaque OXT (98% identical), pig OXT (89% identical), rat Oxt (88% identical), mouse Oxt (87% identical), guinea pig OXT (86% identical), rabbit OXT (82% identical), tropical clawed frog oxt (66% identical), zebrafish oxt (54% identical), zebrafish avp (50% identical). Paralogues in human: AVP (71% identical).
Diseases named in the same sentence as OXT in open-access papers:
OXT is named in the same sentence as 181 diseases in open-access papers, as found by Europe PMC text mining. Sharing a sentence is not in itself a finding about the gene and the disease. The quoted sentences say what the papers report.
Anxiety (158 papers, 2009 to 2026). Intense feelings of nervousness, tension, or panic often arise in response to interpersonal stresses. "Another brain structure associated with the regulation of anxiety levels, due at least in part to the neural production of neuroactive molecules involved in anxiety control, such as OXT and CRF, is the hypothalamus." (PMID 40141416, 2025). "Elevated OXT levels have been linked to reduced anxiety and depressive symptoms, highlighting its potential as a therapeutic target for mood disorders." (PMID 39347144, 2024). "In particular, OXT-deficient mice exhibited high levels of anxiety-related behavior in an elevated plus maze test, which was reversed through OXT administration." (PMID 37887270, 2023). "In clinical use, salivary OXT levels were inversely correlated with separation anxiety symptoms and be positively associated with the separation anxiety scores in children." (PMID 38017588, 2023). "Oxytocin (OXT) is a hormone associated with social bonding and reproduction, and plays a role during and after childbirth, as well as in anxiety and depression." (PMID 37630700, 2023). "It is also possible that other measures associated with OXT functions related to attachment, stress or anxiety would have been insightful." (PMID 36042529, 2022). "Kamikihi-to (KKT), a Japanese traditional herbal (Kampo) medicine composed of 14 herbal ingredients, is clinically prescribed for patients with psychological symptoms, including anxiety, depression, and insomnia, and it has been associated with OXT expression." (PMID 36110514, 2022). "In general, while the central activity that mobilizes AVP appears to be associated with an increase in surveillance, anxiety, excitation and activation, OXT has behavioral and neural effects related to anxiety reduction, relaxing, growth and restauration." (PMID 34805562, 2021). "Consistent with the important role of OXT in social behaviour promotion and stress regulation, OXT dysregulation has been associated with anxiety and autism spectrum disorders (ASD)." (PMID 34040156, 2021). "The oxytocin (OXT) system has been strongly implicated in the regulation of social behaviour and anxiety, potentially contributing to the aetiology of a wide range of neuropathologies." (PMID 34040156, 2021). "This is accomplished due to the fact that OXT shows a significant association with the limbic system, including the amygdala, associating it with a decrease in anxiety and the neuroendocrine response to stress in social interactions." (PMID 34805562, 2021). "Although the effects of peripheral OXT on social interaction remain less well understood, its physiological and behavioral effects associated with stress suggest a potential peripheral component in alleviating anxiety triggered by novel social encounters." (PMID 40262904, 2025). "Research indicates that lower OXT levels are closely associated with anxiety and depression and may impair social cognition and prosocial behavior." (PMID 40635450, 2025). "Oxytocin (OXT) is a neuropeptide that has been associated with neurological diseases like autism, a strong regulating activity on anxiety and stress-related behavior, physiological effects during pregnancy and parenting, and various cellular effects in neoplastic tissue." (PMID 36263085, 2022). "The neuropeptide oxytocin (OXT) has been implicated in many behavioral and physiological processes, like the formation of parent-offspring bonding, labor and milk-letdown, social interaction, general anxiety, and stress-coping." (PMID 36263085, 2022). "To investigate whether brain OXT is causally related to the remediating effects of FLX + EE we tested the effects of OXT-A treatment on anxiety- and depression-like behavior as well as HPA-axis function." (PMID 33875712, 2021). "In addition, this study concluded that low basal OXT levels were associated with greater expression of anxiety and insecurity during stressful situations." (PMID 33902711, 2021).
Anxiety (continued). "Another study in humans found that higher blood OXT levels after a stressful interpersonal task were associated with more anxiety, suggesting that oxytocin could be a marker of distress." (PMID 32325673, 2020). "Oxytocin has been known to act as an anxiolytic and the CeA has been implicated in anxiety and fear responses, but the loci of the anxiolytic action of OXT in the context of social isolation remain unclear." (PMID 30158853, 2018). "Our analysis reveals defects in anxiety- and social-related behavioral responses in adult mutants, which were associated with Otp-dependent developmental neuropeptide switching in a subset of spinal cord-projecting parvocellular OXT neurons." (PMID 28094761, 2017). "It was hypothesized that both AVP and OXT would have preventative effects on social stress-induced deficits in social behavior and increased anxiety and that these effects would be associated with changes in TNFα and/or IFNγ in juvenile F2 females." (PMID 28018290, 2016). "These included genes expected to be related to estrous behavior as they influence states like socio-sexual behavior, anxiety, stress and feeding motivation (OXT, AVP, POMC, MCHR1), but also genes whose association with estrous behavior is novel and warrants further investigation." (PMID 21504592, 2011). "Interestingly, chronic OXT also triggered the release of the splice variant sCRFR2α into the cerebrospinal fluid (CSF), and we further found that sCRFR2α levels in CSF positively correlated with anxiety-like behavior." (PMID 34035479, 2023). "However, MS after exposure to stressful environment during pregnancy will reduce stress susceptibility and anxiety behavior of offspring, and the mechanism may be related to changes of the serum concentration of 17-beta-oestradiol, OXT and Erβ/Erα ratio." (PMID 38017588, 2023). "Via reduction of increased symptoms of stress, anxiety, and social isolation commonly associated with alcohol withdrawal, increased OXT system activity could potentially lead to a reduction in the severity of withdrawal symptoms and thereby aid in the prevention of alcohol addiction relapse." (PMID 36077337, 2022). "Interestingly, carriers of OXT variant rs4813627 GG are suggested to benefit from maternal verbally aggressive behavior, as these carriers show decreased anxiety sensitivity and SDQ emotional symptoms at age 11–12, after exposure to maternal verbally aggressive behavior, compared to GA/AA carriers." (PMID 31065789, 2020). "Accumulating evidence suggests that the OXT/OXTR system plays important roles in anxiety and depression." (PMID 41530867, 2026). "A 0.1 mg/kg dose of OXT blocked the CORT-induced increase in anxiety-like behavior (open field test) and depression-like behavior (forced swimming test), whereas the 1 mg/kg dose did not." (PMID 41756013, 2026). "Animal models and human studies have shown that OXT has anti-anxiety effects and CRH induces depression." (PMID 40559398, 2025). "Gene expression analysis of feeding-related genes (AgRP, NPY, OXT) and those involved in regulating stress and anxiety (DOR and MC3R) were differentially regulated in the VPA rats." (PMID 40004532, 2025). "Bosch mentions that OXT and the neuropeptide arginine vasopressin modulate peripartum anxiety and, thus, maternal aggression." (PMID 40510376, 2025). "OXT has a calming effect on the body and reduces anxiety, while CRH activates the HPA axis and helps the body cope with stress." (PMID 40559398, 2025). "While the involvement of neuronal OXTR-mediated signalling in anxiety-related and multiple other behaviors has been extensively studied the contribution of astrocytic OXT signaling has received limited attention until now." (PMID 39702695, 2025). "In summary, deletion of Trpc5 from OXT neurons recapitulates the behavioral deficits seen in the humanized Trpc5K34del mice, including anxiety-like behavior, reduced sociability, impaired maternal behavior, and postpartum depression-like behavior." (PMID 38959890, 2024).
Anxiety (continued). "In patients with depression, plasma OXT levels are significantly negatively correlated with anxiety symptoms." (PMID 38654385, 2024). "The intraperitoneal or intranasal administration of OXT suppresses lipopolysaccharide (LPS)-induced anxiety-related behavior in mice following a decrease in plasma corticosterone levels." (PMID 37887270, 2023). "The OXT/OXTR signaling is implicated in a variety of normal behaviors, including social interaction, anxiety-related behavior, depression, maternal behavior, aggression, mating, attachment, and sexual behavior." (PMID 37153633, 2023). "In healthy subjects, intranasal administration of synthetic OXT reduces anxiety levels and broadly promotes human social behavior." (PMID 37445607, 2023). "OXT microinjection in CeA promoted social preference and reduced the anxiety levels, whereas CeA infusion with OXTR-antagonist dose-dependently reduced sociality and increased anxiety." (PMID 38017588, 2023). "Experimental induction of alternative splicing mimicked the anxiogenic effects of chronic OXT, while sCRFR2α-knock down reduced anxiety-related behavior of male rats." (PMID 34035479, 2023). "The neuropeptide oxytocin (OXT) has generated considerable interest as potential treatment for psychiatric disorders, including anxiety and autism spectrum disorders." (PMID 34035479, 2023). "While knockdown of sCRFR2α within the PVN using GapmeRs reduced anxiety, local upregulation of alternative splicing of Crfr2α using TSBs increased anxiety, thus recapitulating the effect of chronic OXT." (PMID 34035479, 2023). "We then conducted the in vivo mouse study, and we found that prenatal exposure to MPA triggers OXT suppression as well as autism- and anxiety-like behaviors in offspring." (PMID 35370982, 2022). "We also found that intranasal OXT decreased post-task state anxiety in line with previous studies showing its anxiolytic effects." (PMID 36053298, 2022). "While reduced hypothalamic OXT expression was observed together with alterations in social behavior and anxiety-like behavior in individually compared to socially housed animals, diet did not affect OXT expression." (PMID 35573304, 2022). "In the BACHD mouse model, OXT plasma level is lower than in wild-type littermates with increased depressive-, anxiety-like and social behavior." (PMID 36187357, 2022). "Many recent studies report that OXT is likewise involved in socio-physiological functions, such as stress reduction, anxiety relief, feeding suppression, social recognition, and trust building." (PMID 36110514, 2022). "This, since a negative correlation was found between levels of familiar adjustment to support the youth with anxiety symptoms and the reduction of OXT levels in this population." (PMID 34805562, 2021). "OXT is involved in the regulation of anxiety and fear, and, interestingly, several neural structures involved in fear extinction express OXT-specific receptors." (PMID 34576161, 2021). "OXT concentrations in the cerebrospinal fluid were significantly higher than in the plasma, and patients with higher anxiety scores had lower CSF OXT concentrations than controls." (PMID 33920547, 2021). "Taken together, our findings confirm and extend earlier research demonstrating OXT as an important player in the regulation of anxiety and depression during the postpartum period." (PMID 33875712, 2021). "The activity of OXT plays a key role in societal bearing, anxiety, mood control, and stress modulation." (PMID 33920547, 2021). "The functional roles of septal OXT signaling in anxiety and mood regulation remain to be defined, and the involved downstream targets await identification." (PMID 34489531, 2021). "Recent work has demonstrated that OXT in the mPFC of male rats attenuates anxiety-related behavior engaging GABAergic neurons, which modulate neuronal activation in the BLA and CeA." (PMID 34576161, 2021).